FES (FES proto-oncogene, tyrosine kinase)
Diseases named in the same sentence as FES in open-access papers (continued):
Sharing a sentence is not in itself a finding about the gene and the disease.
cancer (18 papers, 2014 to 2025). A tumor composed of atypical neoplastic, often pleomorphic cells that invade other tissues. "Briefly, FES expression was found to be positively associated with cancer cell proliferation and invasion among patients with high-grade tumors but not among those with low-grade malignancies." (PMID 28952025, 2018). "However, in subgroup analyses based on tumor grade, elevated FES expression was associated with a lower metastasis-free survival rate for patients with high-grade cancer (p = 0.021)." (PMID 28952025, 2018). "For example, the increased FES kinase in severe COVID‐19 can be addressed by repurposing Fostamatinib (a cancer drug) with the purpose of reducing organ damage via inhibition of TNF, IL‐8 and aggressive action of GM‐CSF." (PMID 36537107, 2023). "Looking at the top 5 coding mutations, for example, we noted that corresponding genes (FES, TNFSF15, MSRB1, HRAS, and SLC1A7) have all been experimentally implicated in cancer as drivers." (PMID 32859160, 2020). "In the present investigation, we initially suspected that FES was acting as a tumor suppressor, because its expression in cancer cells was significantly lower than in normal urothelial cells." (PMID 28952025, 2018). "It is possible that the role of FES during the initial carcinogenesis in normal epithelium differs from that in cancer aggressiveness in later stages of the disease." (PMID 28952025, 2018). "Regression analysis suggested a positive correlation between FES expression and PI in human cancer tissues when all patients were considered together; however, this relationship was not statistically significant (r = 0.125, p = 0.068)." (PMID 28952025, 2018). "The relationship between FES expression and cancer aggressiveness was investigated using 3 cell lines (T24: corresponding to grade 3, 5637: corresponding to grade 2, and RT4: corresponding to grade 1) and 203 tissues derived from human bladder malignancies." (PMID 28952025, 2018). "Proliferation, invasion, and migration of cancer cells were assessed following the knockdown (KD) of FES expression by the siRNA method." (PMID 28952025, 2018). "BRD9 inhibition by I-BRD9 in Kasumi-1 cells resulted in lower expression of various cancer- associated genes (CLEC1, DUSP6, FES and SAMSN1)." (PMID 28714904, 2017). "Many of the identified peptide substrates, such as the FER/FES kinases, are involved in one specific task such as cell adhesion, an important process in cancer metastasis." (PMID 28978141, 2017). "Finally, the two compounds that target FES are antineoplastic drugs, and thus, can have severe side effects at therapeutic doses for cancer." (PMID 36055211, 2022). "We speculate that the significance of FES expression in cancer prognosis can be explained by its grade-dependent activities." (PMID 28952025, 2018). "The original identification of FES as a retroviral oncogene underscores its potential role in cancer; however, understanding of its function has been complicated by subsequent research that has implicated FES in both tumor-promotive and tumor-suppressive roles." (PMID 28952025, 2018). "FES expression was clearly decreased by KD in all cancer cell lines." (PMID 28952025, 2018). "We, therefore, speculate that carcinogenesis disturbs the cell–cell and cell–matrix interactions in which FES is involved in normal urinary bladder urothelium, leading to reduced FES expression in cancer cells, especially those of high-grade tumors." (PMID 28952025, 2018). "FES encodes the tyrosine protein kinase Festival (Fp), a non-receptor tyrosine kinase that is involved in cell proliferation, differentiation, and migration, and is reportedly hyperactivated in cancer." (PMID 41415030, 2025).
cancer (continued). "Furthermore, key regulators of FES-related activities may be stimulated or inhibited in high-grade cancers." (PMID 28952025, 2018). "Besides, FES expression in cancer cells may be increased by changes in the surrounding microenvironment." (PMID 28952025, 2018). "However, FES levels tended to positively correlate with cancer cell proliferation and invasion." (PMID 28952025, 2018). "The eight cross-cancer CpGs were annotated to genes involved in transport (KCNA3, KCNAB3 and TRAPPC1), signal transduction (AGAP3 and LIME1), microtubule assembly (FES and SHROOM1), and metal binding (FURIN and AGAP3)." (PMID 35710732, 2022). "Among the genes listed in the COSMIC50 database for cancer, seven blood lifespan cis-eGenes (ALDH2, BCL3, CDKN2A, FES, HIST1H3B, SH2B3, and SMARCA4) were identified (fold enrichment = 1.4, P = 0.22, hypergeometric test)." (PMID 32358504, 2020). "Down-regulated genes such as MMP2, MAPK1, TBFRS7, REL A, SAFB, FES identified GO terms listed as TGF-beta signaling, angiogenesis, IL-4 signaling, cartilage development and cancer-related pathways." (PMID 24756038, 2014). "A multivariate model including all clinicopathological features identified muscle invasion (pT2 and 3; HR = 5.4, 95% CI = 2.24–13.03; p < 0.001) but not cancer cell FES expression (HR = 1.3, 95% CI = 0.52–2.97; p = 0.617) as an independent predictor of subsequent metastasis." (PMID 28952025, 2018). "Furthermore, a subsequent analysis on the possible role of the altered genes in CRC and IPD data sets in the survival of cancer patients (TCGA-COAD data sets) pointed to a significant influence on survival for eight of these genes (TUBB6, PAK6, SULT1A1, SLC11A1, TRAP1, FAM50B, SPON2, FES)." (PMID 34885088, 2021).
tumor (14 papers, 2006 to 2024). "Expression of FES was previously shown to be associated with increased tumor proliferation, angiogenesis, the presence of circulating tumor cells and macrophage infiltration, suggesting its diagnostic and recurrence monitoring potential." (PMID 39136024, 2024). "It was also shown that the increased FES expression was associated with a more aggressive tumor and shorter recurrence-free survival following surgical resection." (PMID 32795296, 2020). "A positive association was also observed between FES expression level and tumor cells invasion in patients with high-grade tumors." (PMID 32795296, 2020). "We have previously shown by modulating neutrophils with an FES inhibitor, we affected the tumor progression and the overall survival in preclinical models." (PMID 36969004, 2023). "The FES gene, a proto-oncogene, is frequently amplified in BrCa58,59 and its overexpression is attributed to tumour growth, angiogenesis and metastasis." (PMID 35710732, 2022). "The results demonstrated that the expression levels of CCNE1, E2F1, ARHGAP11A, RUNX1T1 and FES displayed significant correlation with the tumor stage in patients with NSCLC." (PMID 33613291, 2021). "Reportedly, aberrantly activated FES is related to the proliferation, migration, and invasion of several neoplasms." (PMID 32256211, 2020). "The array CpG whose methylation was most significantly increased with increasing tumor stage was in the FES gene and array methylation was significantly correlated with Sequenom methylation (rho = 0.68, P = 1.1E-12, n = 85)." (PMID 20686660, 2010). "These opposite functions of FES in different tumor cells may be due to its double-sided roles as a proto-oncogene or tumor suppressor." (PMID 32256211, 2020). "Although the overexpression of FES had been historically considered to promote the proliferation, migration, and invasion of tumor cells due to its proto-oncogene characteristics, our results showed that FES overexpression was able to inhibit the proliferation, migration, and invasion of OS cells." (PMID 32256211, 2020). "The FES was significantly down regulated in tumor cells compared with normal urothelial cells." (PMID 32795296, 2020). "However, the notion that FES acts as a tumor suppressor in breast epithelial cells has been recently proposed." (PMID 32256211, 2020). "The feline sarcoma oncogene protein (FES) is a non-receptor tyrosine kinase implicated in both oncogenesis and tumor suppression." (PMID 28952025, 2018). "In addition, tumor onset in the mouse mammary tumor virus–polyomavirus middle T transgenic mouse model of breast cancer was found to be accelerated as a result of FES knockout." (PMID 28952025, 2018). "FES is discussed as a proto-oncogene as well as a tumor suppressor." (PMID 28714904, 2017). "The FeS-glucose oxidase@paclitaxel (abbreviated as FGP) gathered in the tumor tissue could broke down into smaller FeS-GOx nanodots with the unique ability to infiltrate into the depths of the tumor tissue due to small size." (PMID 36105309, 2022). "The negative association that we established between FES expression and tumor grade supported this hypothesis." (PMID 28952025, 2018). "Taken together, FES, regulated by its upstream FYN and β catenin, might coordinately exert a tumor suppressor effect in OS cells." (PMID 32256211, 2020). "FES, and its upstream FYN and β catenin, might coordinately exert a tumor suppressor effect in OS cells." (PMID 32256211, 2020). "FES, regulated by its upstream FYN and β catenin, might coordinately exert a tumor suppressor effect in OS cells." (PMID 32256211, 2020).
neurological disease (1 paper, 2023). "Three target genes (CNIH4, MTUS1, and FES) were enriched in neurological disease-related network." (PMID 38092781, 2023).
FES also shares sentences with these, for which no sentence is quoted: colorectal cancer (2 papers); myeloid leukemia (2); myopathies (2); rheumatoid arthritis (2); schizophrenia (2); acute myeloid leukemia (1); Alzheimer disease (1); amyotrophic lateral sclerosis (1); angina (1); attention deficit-hyperactivity disorder (1); autism spectrum disorder (1); bipolar disorder (1); Charcot-Marie-Tooth disease (1); COVID-19 (1); Diarrhea (1); endothelial dysfunction (1); esophageal squamous cell carcinoma (1); Friedreich ataxia (1); Fundus dystrophy (1); generalized anxiety disorder (1); glioma (1); Hyperglycemia (1); Immunodeficiency (1); Iron overload (1); ischemic stroke (1); lupus (1); nemaline myopathy (1); nephronophthisis (1); nephrotic syndrome (1); non-syndromic intellectual disability (1).
A further 6 diseases each share a sentence with FES in 1 paper.